GALNT12 (polypeptide N-acetylgalactosaminyltransferase 12)
Description:
Catalyzes the initial reaction in O-linked oligosaccharide biosynthesis, the transfer of an N-acetyl-D-galactosamine residue to a serine or threonine residue on the protein receptor. Has activity toward non-glycosylated peptides such as Muc5AC, Muc1a and EA2, and no detectable activity with Muc2 and Muc7. Displays enzymatic activity toward the Gal-NAc-Muc5AC glycopeptide, but no detectable activity to mono-GalNAc-glycosylated Muc1a, Muc2, Muc7 and EA2. May play an important role in the initial step of mucin-type oligosaccharide biosynthesis in digestive organs.
Synonyms: GalNAc-T12; CRCS1
Tractability: Small molecule: a structure with a bound ligand is known. Antibody: UniProt predicts a signal peptide or a membrane-spanning region; the Human Protein Atlas places it where antibodies can reach. PROTAC: ubiquitination databases record sites on it.
Gene: Protein-coding gene on chromosome 9 (98,807,613 to 98,851,266, forward strand). Ensembl gene ENSG00000119514.
Subcellular location: Golgi apparatus membrane
Subcellular location (Human Protein Atlas): Plasma membrane; Cell Junctions; Nucleoplasm
Pathways (Reactome):
Disease: Defective GALNT12 causes CRCS1
Metabolism of proteins: O-linked glycosylation of mucins
Gene Ontology:
Molecular function: protein binding; polypeptide N-acetylgalactosaminyltransferase activity
Biological process: protein O-linked glycosylation; protein O-linked glycosylation via N-acetyl-galactosamine
Cellular component: Golgi apparatus; Golgi membrane
Genetic constraint (gnomAD): Loss-of-function variants: 38 observed, 47.24 expected, observed/expected ratio (o/e) 0.8, 90% interval 0.62 to 1.05. The upper end of that interval is the gene's LOEUF score, 1.05, which puts it in group 4 of 6, group 1 being the genes least tolerant of losing a copy. Missense variants: 691 observed, 681.69 expected, observed/expected ratio (o/e) 1.01, 90% interval 0.95 to 1.08. Synonymous variants: 293 observed, 270.16 expected, observed/expected ratio (o/e) 1.08, 90% interval 0.99 to 1.2.
Gene-disease validity (ClinGen):
ClinGen rates the evidence that GALNT12 causes each of these diseases.
colorectal cancer, susceptibility to, 1 (autosomal dominant): Limited. Any colorectal cancer in which the cause of the disease is a mutation in the GALNT12 gene.
Homologues: Orthologues: chimpanzee GALNT12 (99% identical), macaque GALNT12 (97% identical), dog GALNT12 (91% identical), pig GALNT12 (88% identical), guinea pig GALNT12 (87% identical), mouse Galnt12 (85% identical), rat Galnt12 (85% identical), rabbit GALNT12 (72% identical), tropical clawed frog galnt12 (68% identical), zebrafish galnt12 (65% identical), Caenorhabditis elegans gly-5 (41% identical), Drosophila melanogaster Pgant9 (39% identical), and 2 more. Paralogues in human: GALNT4 (55% identical), GALNT6 (42% identical), GALNT15 (41% identical), GALNT3 (41% identical), GALNT13 (39% identical), GALNT2 (39% identical), GALNT1 (38% identical), GALNT10 (37% identical), GALNT16 (35% identical), GALNT5 (35% identical), GALNTL6 (35% identical), GALNT11 (34% identical), and 7 more.
Diseases named in the same sentence as GALNT12 in open-access papers:
GALNT12 is named in the same sentence as 30 diseases in open-access papers, as found by Europe PMC text mining. Sharing a sentence is not in itself a finding about the gene and the disease. The quoted sentences say what the papers report.
colorectal cancer (13 papers, 2013 to 2023). A primary or metastatic malignant neoplasm that affects the colon or rectum. "Further clinical studies have shown a correlation between pathogenic mutations in GALNT12 and colorectal cancer." (PMID 38201513, 2023). "It is also involved in “Defective GALNT12 causes colorectal cancer 1 (CRCS1)” and “Defective GALNT3 causes familial hyperphosphatemic tumoral calcinosis (HFTC)” pathways based on the Reactome Pathways database." (PMID 35439935, 2022). "Several significant pathways were identified from the submitted data, including a pathway that caused colorectal cancer by defective GALNT12." (PMID 34573430, 2021). "In addition, NRG1 is involved in constitutive signalling by aberrant PI3K in cancer, CSNK1A1L in signalling by WNT in cancer, and MUCL1 in defective GALNT12 causes colorectal cancer." (PMID 31797963, 2019). "Additionally, one nonsense and six more missense variants, which encoded essentially inactive GALNT12 enzymes, were exclusively found among colorectal cancer patients, suggesting that this gene has a role in this tumor." (PMID 26309160, 2015). "Single mutations were identified in MEN1 for gastric cancer, MSH6 for colorectal cancer, CDKN2A for pancreatic cancer, and EPCAM/TSC2/GALNT12 for breast cancer." (PMID 38201513, 2023). "Interestingly, GALNT12, DDT, and ARNT2 have been found to be over-represented in cancer, including colorectal cancer among others, with ARNT2 showing promoter hypermethylation in hepatoma cells." (PMID 33266012, 2020).
colon cancer (9 papers, 2015 to 2024). "Although GalNAc transferase 12 gene plays a role in the initial step of the synthesis of mucine-like oligosaccharides, in the colon and other organs, somatic mutations in GALNT12 in colon cancer have been reported to be rather rare." (PMID 33245729, 2020). "GALNT12 mutation inactivated the normal function of the GALNT enzyme in initiating mucin type O-linked protein glycosylation in colon cancers." (PMID 29970122, 2018). "Galnt12 encodes an acetylgalactosaminyl transferase and polymorphisms in the gene are associated colonic cancer." (PMID 27891095, 2016). "In 2009 Guda and colleagues sequenced GALNT12 in colon cancer cell lines detecting two somatic missense mutations in two different colorectal cell lines." (PMID 26309160, 2015). "Mutations in gene GALNT12 have been found in colonic cancers and also suggested to predict CRC and this enzyme is initiating mucin type O-linked protein glycosylation and may contribute to a subset of colon cancers." (PMID 29547645, 2018). "A later study in a familial form of colon cancer also was able to zoom in to a region around 9q22.2-31.2, in which aside the gene of HABP4 only three other genes are found, which seem to be less likely candidates for oncoproteins or tumor suppressors (ZNF367, GABBR2 and GALNT12)." (PMID 33245729, 2020).
breast carcinoma (5 papers, 2016 to 2025). "In our cohort, we identified a 14-bp nucleotide deletion c.171_184del in GALNT12 in a patient with breast cancer." (PMID 38201513, 2023). "Based on Cancer Genetic Markers of Susceptibility breast cancer study (CGEMS), 3 SNPs located between ANKS6 and GALNT12 were identified as significantly associated with breast cancer." (PMID 33240314, 2020). "The potential impact of LOF mutations in the GALNT12 gene on breast cancer risk has not yet been studied." (PMID 38201513, 2023).
colorectal cancer 1 (3 papers, 2022). "Of note, the enrichment analysis results showed that AC009095.1 participates in the pathway, and defective GALNT12 causes colorectal cancer 1 (CRCS1), but there is no relevant evidence to support it." (PMID 36185274, 2022).
glioblastoma (3 papers, 2022 to 2024). The most malignant astrocytic tumor (WHO grade IV). "The researchers found that polypeptide N-Acetylgalactosaminyltransferase 12 (GALNT12) expression was highly linked with poor prognosis in glioblastoma, demonstrating that GALNT12 in U-87 MG glioblastoma cells mediates cell proliferation, migration, and invasion through the PI3K/Akt/mTOR pathway." (PMID 39728102, 2024).
IgA nephropathy (2 papers, 2021 to 2024). "Among inflammatory skin diseases, atopic dermatitis was found to increase the risk of IgA nephropathy, which may result from the decrease of GALNT12 and C1GALT1C1 expression and the increase of aberrant IgA1 production." (PMID 39119579, 2024).
prostate carcinoma (2 papers, 2024 to 2025). A carcinoma that arises from epithelial cells of the prostate gland. "Although its role in carcinogenesis has been reported in several studies, in prostate cancer, GALNT12 has been shown to suppress tumor cell proliferation, migration, invasion, cell division, and bone‐specific metastasis." (PMID 40488817, 2025).
adenoma (1 paper, 2017). A neoplasm arising from the epithelium. "Since phenotypes of the described carrier families showed not only CRC but also a polyp history, we hypothesized that GALNT12 could be involved in adenoma predisposition and consequently, in hereditary polyposis CRC syndromes." (PMID 29095867, 2017).
atopic dermatitis (1 paper, 2024). "In the combined dataset, the expression of galactose-deficient IgA1-associated genes (including GALNT2, GALNT12, C1GALT1, C1GALT1C1 and ST6GALNAC2) were compared between atopic dermatitis patients and healthy controls." (PMID 39119579, 2024). "In the combined microarray dataset, the expression levels of GALNT12 and C1GALT1C1 in atopic dermatitis patients were significantly lower compared with controls (p = 2.3e−9; p = 0.00067), which may contribute to an increase in aberrant IgA1 synthesis." (PMID 39119579, 2024).
bladder cancer (1 paper, 2024). "FASN, MAP2 and BMP6 were highly expressed in bladder cancer, while GPC2, CNOT6L, GALNT12 and CARD10 were expressed at low levels in bladder cancer." (PMID 38218866, 2024).
cervical cancer (1 paper, 2025). A primary or metastatic malignant neoplasm involving the cervix. "This study utilized bioinformatics analysis based on public databases to identify key prognostic genes associated with cervical cancer, including GALNT12, GCNT4, and NPL." (PMID 40352586, 2025). "GALNT12 and GCNT3 had HRs greater than 1, indicating that they were risk factors for cervical cancer, whereas GCNT4 and NPL had the reverse effect." (PMID 40352586, 2025). "Core 2 O-glycans are the basis for many sialylations, and the GALNT12 gene may have a significant impact on the sialylation process by catalyzing the synthesis of core 2 O-glycans, thereby affecting the prognosis of cervical cancer." (PMID 40352586, 2025). "This study identified three key prognostic sialylation-related genes, GALNT12, GCNT4 and NPL, which showed significant differences in expression between cervical cancer samples and normal samples." (PMID 40352586, 2025). "In this research, GALNT12, GCNT4 and NPL were discovered as sialylation-related prognostic genes in cervical cancer, providing novel pathways for detection and treatment." (PMID 40352586, 2025).
endometrial cancer (1 paper, 2019). Primary or metastatic malignant neoplasm involving the endometrium (mucous membrane that lines the endometrial cavity). "However, there are no reports on the relationship between MPL, GALNT12 and endometrial cancer to date." (PMID 30886832, 2019). "In addition, we identified 2 patients who had a deleterious germline mutation in Lynch syndrome genes (MLH1 and MLH2), and another 8 patients harbored germline mutations of 6 non-Lynch syndrome genes (MUTYH, GALNT12, POLE, MPL, ATM, and ERCC4) which may be associated with endometrial cancer." (PMID 30886832, 2019).
hereditary colorectal cancer (1 paper, 2016). "In the majority of hereditary colorectal cancer (CRC) families, GALNT12 variants were characterized as highly penetrant variants that influence the pathogenesis of CRC, but little is known regarding the genotypic and allelic frequencies of GALNT12 in different racial/ethnic groups." (PMID 27322213, 2016).
non-Hodgkin lymphoma (1 paper, 2016). Distinct from Hodgkin lymphoma both morphologically and biologically, non-Hodgkin lymphoma (NHL) is characterized by the absence of Reed-Sternberg cells, can occur at any age, and usually presents as a localized or generalized lymphadenopathy associated with fever and weight loss. "In two-hundred and forty-four follicular lymphoma (FL) cases recognized during a population-based case-control study of non-Hodgkin lymphoma (NHL), five genes (GALNT12,BMP7, DUSP2,GADD45B, andADAM17) were found associated with the overall survival of FL and control of B-cell activity." (PMID 27322213, 2016).
cancer (12 papers, 2015 to 2025). A tumor composed of atypical neoplastic, often pleomorphic cells that invade other tissues. "We hope that our study and others will contribute to a more thorough investigation about the relationship between mutations in the GALNT12 gene and cancer susceptibility." (PMID 38201513, 2023). "Potentially pathogenic variants were found in five Cancer Gene Census germline genes: GALNT12, POLE, MPL, ATM, and ERCC4." (PMID 30886832, 2019). "Studies have shown that the expression of the GALNT12 gene is altered in several types of cancer." (PMID 40352586, 2025). "Other genes include GALNT12 which encodes for an enzyme involved in O-linked glycosylation, and RNASEL, a ribonuclease involved in interferon signaling, which have both been implicated as cancer risk genes in population studies." (PMID 39844333, 2025). "We further demonstrated that GALNT12-BMP signaling decreased integrin αVβ3 expression, suppressed the binding of cancer cells to the vitronectin in bone matrix, and thus restrained bone metastasis of PCa." (PMID 38385080, 2024). "Currently, it is not clear how to use low cancer risk genes in management and risk counseling (NBN, XRCC2, GALNT12, etc.), since recommendations should be based either way on the personal and family history of cancer." (PMID 26484312, 2015).
tumor (9 papers, 2015 to 2025). "In this study, the expression of the NPL gene showed a trend of first increasing and then decreasing during macrophage differentiation, while the GALNT12 gene was expressed in tumor samples during the third stage of macrophage differentiation." (PMID 40352586, 2025). "Previous studies have shown that the high expression of GALNT12 not only promotes the sialylation process but also inhibits natural killer cells, thereby suppressing anti-tumor immune responses." (PMID 40352586, 2025). "Given their tumor‐suppressive roles, it is plausible that GALNT12 and FRMD3 contribute to the favorable prognosis observed in MMR‐mutated UTUC." (PMID 40488817, 2025). "We found that tumor development in bone was significantly promoted in GALNT12 depletion group compared to that in control group." (PMID 38385080, 2024). "Factor 5 was localized at the tumor interface, associated with both epithelial and macrophage cells, and was enriched in pathways related to EMT and immune responses, including Dectin-2 and Defective GALNT12 causes CRCS1." (PMID 41042257, 2025). "Meanwhile, the expression of GALNT12 at specific differentiation stages may contribute to the regulation of macrophage states and indirectly affect tumor progression, though the precise regulatory mechanisms require further investigation." (PMID 40352586, 2025). "Additionally, the GALNT12 gene was highly expressed in tumor samples during the third stage of differentiation, suggesting that it might play an important role during the later stages of macrophage differentiation or in tumor-related phases." (PMID 40352586, 2025). "Additionally, GALNT12 and ST6GALNAC1 are associated within the protein-protein interaction (PPI) network, and this interaction may collaboratively regulate the sialylation process, further influencing tumor cell invasion, metastasis, and immune evasion." (PMID 40352586, 2025).
GALNT12 also shares sentences with these, for which no sentence is quoted: familial hyperphosphatemic tumoral calcinosis (2 papers); hepatocellular carcinoma (2); Alzheimer disease (1); breast tumors (1); familial cancer (1); gastric cancer (1); hepatoid adenocarcinoma (1); inflammatory skin disease (1); Lynch syndrome (1); melanoma (1); neuroblastoma (1); pancreatic cancer (1); polyp (1); rheumatoid arthritis (1).